CD4 (CD4 molecule)
Diseases named in the same sentence as CD4 in open-access papers (continued):
Sharing a sentence is not in itself a finding about the gene and the disease.
sarcoidosis (continued). "Several authors concluded that BALF lymphocytosis and a CD4/CD8 ratio ≥3.5 support the diagnosis of sarcoidosis in patients with a typical clinical picture, obviating the need for further biopsy confirmation, although 10% to 15% of cases have a normal cell count." (PMID 31466346, 2019). "This suggests the CD4/CD8 ratio might reflect the pathology of sarcoidosis as a systemic inflammatory and immunologic disorder." (PMID 30452447, 2018). "In addition, the CD4/CD8 ratio was significantly higher in sarcoidosis (p < 0.001, Mann-Whitney U-test)." (PMID 30452447, 2018). "Sarcoidosis is a multisystem granulomatous disorder of unknown etiology, characterized by accumulation of activated CD4+ T cells in the lungs." (PMID 28955342, 2017). "The absence of granulomatous infection and a markedly elevated CD4:CD8 ratio in bronchoalveolar lavage analysis suggested that the underlying process was sarcoidosis." (PMID 28558711, 2017). "We sought to determine whether sarcoidosis CD4+ T cells also displayed increased levels of apoptosis at baseline by using Annexin V and 7AAD cell-surface staining." (PMID 29234685, 2017). "The mean CD4/CD8 ratio was highest for sarcoidosis compared to other diseases, it was 2.56." (PMID 28245857, 2017). "An alternative hypothesis is that vimentin, together with other proteins, may serve as a self-antigen capable of eliciting cytokine responses from sarcoidosis PBMCs, potentially in a CD4+ T-cell mediated fashion." (PMID 28114394, 2017). "This investigation reports a more complete characterization of sarcoidosis CD4+ T cell function." (PMID 29234685, 2017). "Sarcoidosis is a granulomatous disorder of unknown etiology, characterized by accumulation of activated CD4+ T cells in the lungs." (PMID 28955342, 2017). "Immunoprofiling of local and systemic sarcoidosis CD4+ cells during disease progression reveals an exhausted phenotype, indicating that loss of multiple critical facets of adaptive immune function during disease progression is a key feature of sarcoidosis pathogenesis." (PMID 29234685, 2017). "Results from assessing LS and non-LS-associated variants for susceptibility of CD4+ and CD8+ T-cells and of CD4/CD8 ratio in both healthy and diseased test groups provided considerable evidence for the plausibility of pleiotropy between susceptibility to sarcoidosis and T-cell levels." (PMID 28717140, 2017). "Previous reports have delineated how CD4+ helper T cell subsets, such as Th1, Th2, Th17 and regulatory T cells, cooperate or interfere with each other to orchestrate the progression or control of sarcoidosis." (PMID 26845566, 2016). "Evidence of an elevated CD4+/CD8+ T cell ratio in BALF might be an important guiding factor in sarcoidosis diagnosis." (PMID 26845566, 2016). "Different subsets of CD4+ helper T cells participate in the immunopathogenesis of sarcoidosis." (PMID 26845566, 2016). "Patients with sarcoidosis have clusters of CD4+ T-helper Th1 lymphocytes in affected organs." (PMID 27563474, 2016). "Sarcoidosis is a multisystemic granulomatous disease of unknown etiology characterized by a compartmentalization of CD4+ T helper 1 (Th1)/Th17 lymphocytes and activated monocyte/macrophages in involved organs, predominantly the lungs." (PMID 26240517, 2015). "The hallmark of sarcoidosis is the noncaseating granuloma, which consists of activated macrophages and CD4-helper T lymphocytes." (PMID 25922606, 2015). "An increased ratio between IFN-γ+ Th17 cells and FoxP3+ CD4+ T cells may represent a corresponding feature of sarcoidosis." (PMID 24882950, 2014). "In the present study we also noted Vβ8 T cell expansions in CD4+ PBMC of two sarcoidosis patients." (PMID 24656074, 2014).
sarcoidosis (continued). "From studies of BAL cells we know that lung accumulated immune cells are activated in sarcoidosis patients, further, accumulations of CD4+ cells expressing the T cell receptor (TCR) V gene segment Vα2.3+ are accumulated in BAL fluid (BALF) of HLA DRB1*03+ patients, often with Löfgren’s syndrome." (PMID 24656074, 2014). "This may indicate a strong Th1 immune response in sarcoidosis patients resulting in deviation of CD4+ T cell differentiation from FoxP3+ CD4+ T cells and plain Th17 cells into IFN-γ+ Th17 and Th1 cells." (PMID 24882950, 2014). "Furthermore, we found a high degree of correlation between fractions of IFN-γ+ Th17 and Th1 cells, and the ratio of IFN-γ+ Th17/FoxP3+ CD4+ T cells was prominently increased in sarcoidosis compared to other DPLDs or HCs." (PMID 24882950, 2014). "In the present study, the FoxP3+ fractions of CD4+ T cells in sarcoidosis were lower than in HC." (PMID 24882950, 2014). "After BALF CD4+ lymphocytes were stimulated with ionomycin and phorbol 12-myristate acetate, there was an appreciable increase in secreted IFNγ but a decrease in IL-4 expression in sarcoidosis patients compared to controls." (PMID 26464848, 2013). "The Th17 cell population in PBMCs was increased in sarcoidosis patients (1.61% ± 1.09%) compared with HCs (0.51% ± 0.43%) (p < 0.05), whereas CD4+ CD25high Foxp3+ Tregs were decreased in sarcoidosis patients (0.95% ± 0.91%) compared to HCs (2.68% ± 2.15%) (p < 0.05)." (PMID 24177566, 2013). "Increased active CD4 T lymphocytes have been shown in tissues with sarcoidosis." (PMID 24381778, 2013). "Moreover, increased cytokine profiles have been verified by increased BALF IFNγ+/IL-4+ CD4+ T cell ratios in sarcoidosis patients." (PMID 26464848, 2013). "Finally, mo-DCs from sarcoidosis patients induce more TNFα in co-cultures with allogeneic CD4+ T cells, compared to mo-DCs from healthy controls." (PMID 22513006, 2012). "The roles of cathepsins S and L on the functions of CD4+ may have a direct influence on sarcoidosis development." (PMID 21251246, 2011). "In addition to alveolar macrophages (AMs), sarcoidosis patients display increased numbers of CD4+ T lymphocytes in their lungs." (PMID 20813038, 2010). "However, the number of lymphocytes and the CD4/CD8 ratio in bronchoalveolar lavage (BAL) fluid are highly variable in sarcoidosis." (PMID 19242869, 2009). "However, the number of lymphocytes as well as the CD4/CD8 ratio in BAL fluid (BALF) are highly variable in sarcoidosis." (PMID 19242869, 2009). "Sarcoidosis is a granulomatous disorder resulting from an uncontrolled cell-mediated immune reaction characterized by accumulation of activated monocytes/macrophages and CD4 T lymphocytes in all sites of disease activity." (PMID 19242869, 2009). "A CD4+/CD8+ ratio of >3.5 in a patient with a typical clinical and radiological picture is very specific for sarcoidosis and may obviate the need for further invasive diagnostic procedures." (PMID 17166281, 2006). "This is now challenged since the CD4/CD8 ratio in HP can be as high as that seen in sarcoidosis." (PMID 16817954, 2006). "Consequently, the highest CD4/CD8 ratio was in sarcoidosis patients." (PMID 40725075, 2025). "Conversely, in sarcoidosis, BAL provides information on the characteristic cellular profile of the disease, highlighting the presence of T lymphocytes and activated macrophages with an inverted CD4/CD8 ratio, showing high diagnostic confidence for the disease in the appropriate clinical context." (PMID 38337490, 2024). "Additionally, increased proportions of circulating CD4+ T cells with expression of checkpoint molecule programmed death-1 (PD-1) and an exhausted phenotype were found in progressive sarcoidosis relative to patients with disease resolution and healthy controls (HCs)." (PMID 38715030, 2024).
sarcoidosis (continued). "It is known that circulating and BAL-associated CD4+ T cells that produce IFN-γ play an important role in sarcoidosis-associated inflammation and granuloma formation, just as serum and BAL from patients with sarcoidosis are characterized by the increased levels of IFN-γ." (PMID 37189479, 2023). "Indeed, the CD4/CD8 ratio has been used clinically in different scenarios: For example in the diagnosis of sarcoidosis and in chronic granulomatours diseases where a depletion in CD8+ T-cells leading to a higher CD4/CD8 ratio seems to be protective to worse disease presentations." (PMID 35814752, 2022). "CD4 cell levels do not seem to explain the association between sarcoidosis and cryptococcosis." (PMID 35425769, 2022). "Despite emerging evidence that AAV and sarcoidosis are related with regard to dysregulation of the cellular immune system, there are currently no data regarding the adaptive immune cell profiling common to both diseases, also considering IC molecule expression on CD4, CD8 and NK cells." (PMID 36613701, 2022). "Finally, the CD4/CD8 ratio in BALF seems to be lower in CVID than in sarcoidosis (mean, 1.6 vs. 5)." (PMID 34359324, 2021). "The HIF-1 signaling pathway was proven to regulate Th1/Th17 mediated inflammation in sarcoidosis and be linked to imbalance of CD4+/CD8+ in BALF and acknowledged negative prognostics, consistence with the result that the expression of four miRNA had moderate correlation with the ratio of CD4+/CD8+." (PMID 33178707, 2020). "For example, a simultaneously increased BAL fluid level of CCL18 and TGF-β1 secreting CCR6+ CD4+ T-cells would raise clinical suspicion of fibrosing sarcoidosis, and the clinician could consider prescribing anti-fibrotic agents to minimize the damage of future fibrotic scarring." (PMID 33036432, 2020). "Additionally, CD28 controls differentiation of Tregs from naïve CD4 T cells, providing novel mechanisms that may explain progression or remission of sarcoidosis." (PMID 32764642, 2020). "It is possible that a similar unbiased antigen discovery approach utilizing expanded CD4+ T cell clones in the lungs of sarcoidosis patients may lead to the discovery of the inciting antigens that drive CD4+ T cell alveolitis and granulomatous inflammation in sarcoidosis." (PMID 32256501, 2020). "However, at least 5% of sarcoidosis cases shows low CD4+/CD8+ ratio." (PMID 31281552, 2019). "A third subgroup of immune cells, the CD4 (+) CD25 (+) regulatory T cell (Treg) showed an abnormal expansion which may be responsible for the paradoxical suppression of the immune response to tuberculin observed in sarcoidosis." (PMID 29510755, 2018). "Thus, it may be that the persistence of these antigens promotes T cell exhaustion in sarcoidosis CD4+ T cells." (PMID 29234685, 2017). "A further study by the same group demonstrated higher CD4+ T-cell responses towards mKatG in sarcoidosis compared to healthy volunteers with evidence of compartmentalization of response in the lungs of patients, indicating that it may be one of several pathogenic antigen in sarcoidosis." (PMID 28114394, 2017). "The balance between Th1, Th17, and FoxP3+ CD4+ T cell subsets in sarcoidosis remains unclear." (PMID 24882950, 2014). "Furthermore, we found a negative correlation between BALF CD4+ T cell IL-17A expression and BALF CD4/CD8 ratio in sarcoidosis, suggesting that the alveolitis seen in patients is associated with an influx of CD4 T cells with on average merely little production of IL-17." (PMID 20813038, 2010). "Along with the radiographic stage of sarcoidosis, an increase in CD8 and a decrease in CD4 cell count, as well as in CD4/CD8 ratio, and an increase in neutrophil count and percentage in BALF are documented." (PMID 40217830, 2025). "Bronchoscopy with bronchoalveolar lavage (BAL) and cytology revealed a CD4/CD8 ratio of 6.53, further supporting a diagnosis of sarcoidosis." (PMID 40729241, 2025).
sarcoidosis (continued). "CD4 and CD8 were also reported to be connected to fibrotic development, which was observed in HP and sarcoidosis patients." (PMID 40725075, 2025). "CD4/CD8 ratio is a well-established measure of various diseases, such as HIV (ratio is determined from blood) or sarcoidosis (bronchioalveolar lavage)." (PMID 40981339, 2025). "Correlation analysis demonstrated an indirect correlation between CD4 and CD8 cells in IPF and sarcoidosis patients (p < 0.001 = −0.87 and p = 0.042; r = −0.6, respectively)." (PMID 38540243, 2024). "It has been reported patients with sarcoidosis have more intermediate monocytes, which are high in MHC-II expression, responsible for binding and presenting antigens to CD4+ T cells." (PMID 39502781, 2024). "The aim of the present study was to analyse the similarities and differences in CD4+, CD8+, and NK cells in the peripheral blood of patients with fibrotic disease (IPF and PCPF) compared with sarcoidosis and healthy controls (HCs)." (PMID 38540243, 2024). "As suggested by the literature, a higher rate of CD4 and a lower rate of CD8 cells were observed in BAL compared to peripheral blood in sarcoidosis patients." (PMID 38611622, 2024). "The aim of the present study was to analyse the similarities and differences between CD4+, CD8+, and NK cells in the peripheral blood of patients affected by fibrotic disease, IPF, and PCPF compared with sarcoidosis patients and healthy controls." (PMID 38540243, 2024). "Correlation analysis demonstrated an indirect correlation between CD4 and CD8 cells in IPF and sarcoidosis patients." (PMID 38540243, 2024). "In the bronchoalveolar fluid, a CD4:CD8 ratio is typically normal in CVID and elevated (>3.5) in sarcoidosis." (PMID 39359743, 2024). "As for sarcoidosis, also in GLILD a predominance of CD4+ T cells and a marked reduction of regulatory T cells (T-regs) in the lungs have been described." (PMID 39062076, 2024). "In BALF of sarcoidosis patients, a polarisation towards Th17 and Th17.1 cells (able to produce both IL-17 and IFN-γ) has been described, being Th17.1 the predominant CD4+ population." (PMID 39062076, 2024). "The results of this study on the distribution of CD4+ T-cell subpopulations revealed that there was an increased frequency of Tregs in the blood, and of Th17.1 cells in the BALF, of sarcoidosis patients." (PMID 37520566, 2023). "Using logistic regression analysis, we found that if blood CD4+CD31+ T lymphocytes were ≤14.5%, the odds ratio for sarcoidosis progression was 13.78 (p = 0.02)." (PMID 37239108, 2023). "Combined with the elevated ratio of CD4+/CD8+ T cells in bronchoalveolar lavage fluid and other results, the patient was finally diagnosed with sarcoidosis and received corticosteroid therapy." (PMID 37761357, 2023). "In the appropriate clinical and radiographic findings that are compatible with sarcoidosis, an increased total BAL cell counts, CD4+ T cells, and CD4+/CD8+ ratio (> 3.5) strongly supports the diagnosis of the disease." (PMID 36824606, 2023). "A reduction of PB lymphocytes despite increased proliferation of CD4+and CD8+ T cells was observed in patients with chronic active compared with chronic stable sarcoidosis, indicating an increased PB lymphocyte turn-over in patients with deteriorating disease." (PMID 38097354, 2023). "A lymphocytosis due to accumulation of CD4+ T cells, and increased production of pro inflammatory cytokines, for example, TNF-α and IFN-γ, are typically seen in the lungs of individuals with sarcoidosis, a systemic granulomatous inflammatory disease." (PMID 38097354, 2023). "We observed higher levels of IL-2R+ CD4+ T cells in patients with IPF compared to those with CTD-ILDs and sarcoidosis." (PMID 36949950, 2023). "The prevalence of T cells appeared to be elevated in sarcoidosis and CTD-ILDs compared to IPF, with the CD4/CD8 ratio tending towards an increase in sarcoidosis, although not reaching statistical significance." (PMID 36949950, 2023).
sarcoidosis (continued). "reported, in line with our data, that Th17.1 cells constituted approximately 30% of the lung CD4+ T cells and that their frequency was markedly higher in the BALF of sarcoidosis patients than in that of healthy volunteers." (PMID 37520566, 2023). "CD4+PD1+ T cells have been reported in a number of fibrotic diseases including subglottic stenosis, idiopathic pulmonary fibrosis (IPF), and sarcoidosis." (PMID 35371068, 2022). "CD4+ T cells, including Th1 and Th17 cells, are the predominant T-cell subsets in the BALF of sarcoidosis patients." (PMID 35615369, 2022). "Sarcoidosis is a granulomatosis of an unknown etiology, typically presented as a systemic relatively benign disease, characterized by the accumulation of activated T lymphocytes (CD4+) and mononuclear phagocytes with the formation of epithelioid cell granulomas." (PMID 36010289, 2022). "Both CD3+CD4+CD38+ and CD38+ B cell subsets were found to be elevated in BAL as markers of an acute immune response in sarcoidosis patients." (PMID 36203777, 2022). "CD4+PD1+ and CD4+TIGIT+ cell subsets were higher in sarcoidosis than in HC (p = 0.0250 and p = 0.0014, respectively) and higher in MPA than in HC (p = 0.0117 and p = 0.0113, respectively)." (PMID 36613701, 2022). "Although recovery of T cells in the sarcoidosis samples appeared suboptimal, we observed that similarly to the skin, in BAL the majority of T cells were CD4+FOXP3-." (PMID 35668129, 2022). "The PCA plot distinguished the disease clusters: MPA, GPA, sarcoidosis and HC showed that they were separated on the basis of CD4+CTLA4+, CD4+PD1+, CD4+TIGIT+, CD56, CD56+CTLA4+, CD56+TIGIT+, CD8, CD8+CTLA4+ and CD8+PD1+." (PMID 36613701, 2022). "Other interesting cells would be CD4+, CD8+, and CD19+ T cells, which are also known to play an important role in sarcoidosis." (PMID 35563867, 2022). "The model showed CD56+CTLA4+ > 33.29% for 100% of sarcoidosis patients, but CD56+CTLA4+ ≤ 33.29, CD4+PD1+ > 1.55% and CD8+ > 30.7% for 100% of GPA patients." (PMID 36613701, 2022). "CTLA4+NK cells clustered for 100% of sarcoidosis patients according to decision tree analysis, while PD1+CD4 and CD8 cells for clustered for 100% of GPA patients." (PMID 36613701, 2022). "CTLA4+NK cells clustered for 100% of sarcoidosis patients, according to the decision tree analysis, while PD1+CD4 and CD8 cells clustered for 100% of GPA patients." (PMID 36613701, 2022). "We reported for the first time that LNs CD4+ and CD8+ T cells maturation differs depending on the DLCO value in sarcoidosis." (PMID 34943912, 2021). "Peripheral depletion of CD4+, CD8+, and CD19+ T-cells has also been shown to be a characteristic of patients with severe sarcoidosis." (PMID 33718397, 2021). "The AUROC for the CD4 to CD8 ratio was 0.844, which was significantly high in distinguishing between sarcoidosis and the other ILDs." (PMID 34217348, 2021). "Decreased effector CD4+ and CD8+ T cells and increased central memory CD4+ and CD8+ cells in LNs were characteristic for sarcoidosis patients in the advanced disease phase." (PMID 34943912, 2021). "In patients with sarcoidosis, numbers of CD103 CD4+ T-cells in BAL fluid are significantly lower than in other lung diseases." (PMID 32760396, 2020). "In an acute form of sarcoidosis, there are expansions of specific TRAV12-1/TRBV2 T cell receptors expressed on BAL CD4+ T cells, indicating that these T cells are trafficking to and expanding in the lung in response to common antigens." (PMID 32256501, 2020). "CD4+ T cells in the bronchoalveolar lavage (BAL) of CBD and sarcoidosis patients are highly Th1 polarized, and there is a significant increase in inflammatory Th1 cytokines present in the BAL fluid." (PMID 32256501, 2020). "On the other hand, specificity proved to be higher for CD4+ Va2.3+ T-cells compared to the CD4/CD8 ratio in BALF (97 vs. 92%), which will help with the diagnosis of sarcoidosis." (PMID 32760396, 2020).